YOD1 (YOD1 deubiquitinase)
Diseases named in the same sentence as YOD1 in open-access papers (continued):
Sharing a sentence is not in itself a finding about the gene and the disease.
cardiac hypertrophy (1 paper, 2025). "Only the Yod1 mRNA expression level is consistently elevated in these two cardiac hypertrophy models." (PMID 40561034, 2025). "In this study, we further explored the role and regulating mechanism of YOD1 in cardiac hypertrophy." (PMID 40561034, 2025). "We revealed that either cardiomyocyte-specific YOD1 knockout (YOD1CKO) or pharmacological inhibition of YOD1 significantly attenuates Ang II–induced cardiac hypertrophy and dysfunction in mice." (PMID 40561034, 2025). "This study highlights the involvement of YOD1 in mediating cardiac hypertrophy, providing a promising therapeutic target for this disease." (PMID 40561034, 2025). "In this study, we observed that YOD1 was overexpressed in cardiomyocytes during pathological cardiac hypertrophy." (PMID 40561034, 2025). "This study elucidates the role of YOD1 in pathological cardiac hypertrophy." (PMID 40561034, 2025). "YOD1 promotes pathological cardiac hypertrophy by deubiquitinating and stabilizing STAT3 protein." (PMID 40561034, 2025). "Through screening of the Gene Expression Omnibus (GEO) database followed by polymerase chain reaction (PCR) validation, we found that YOD1 expression in cardiomyocytes is up-regulated in pathological cardiac hypertrophy, indicating the involvement of YOD1 in this disease." (PMID 40561034, 2025). "We also demonstrated the protective role of cardiomyocyte-specific knockout and pharmacological inhibition of YOD1 against myocardial hypertrophy, suggesting that cardiac-specific therapy targeting YOD1 may be an attractive strategy for the treatment of cardiac hypertrophy." (PMID 40561034, 2025). "Therefore, we hypothesize that STAT3 serves as a substrate of YOD1 in cardiomyocytes and mediates YOD1’s role in cardiac hypertrophy." (PMID 40561034, 2025). "We demonstrate the role and regulatory mechanism of cardiomyocyte YOD1, a DUB in the OTU family, in cardiac hypertrophy." (PMID 40561034, 2025). "Collectively, we showed that cardiomyocyte YOD1 deubiquitinates and stabilizes STAT3 to drive cardiac hypertrophy, fibrosis, and dysfunction." (PMID 40561034, 2025). "We confirmed that knockout of YOD1 specifically in cardiomyocytes effectively alleviated Ang II– and TAC-induced cardiac hypertrophy." (PMID 40561034, 2025). "Cardiomyocyte-specific knockout of YOD1 reduced Ang II– and TAC-induced cardiac hypertrophy." (PMID 40561034, 2025).
colitis (1 paper, 2024). Inflammation of the colon. "The bone marrow transplantation experiment unambiguously confirmed that the aggravated colitis in Yod1−/− mice was predominantly caused by YOD1 deficiency in hematopoietic cells." (PMID 39333628, 2024). "Together, these results show that YOD1 deficiency aggravates colonic injury in experimental colitis." (PMID 39333628, 2024). "Consistently, the protective function of muramyldipeptide, a NOD2 ligand, in experimental colitis is abolished in mice deficient of YOD1." (PMID 39333628, 2024). "Consistent with the protective role of NOD2 signaling in colitis, deficiency of RIPK2 significantly exacerbated colitis in Yod1+/+ mice." (PMID 39333628, 2024). "Upon stimulation with CHX and TNF-α, a detrimental proinflammatory cytokine underlying mucosal damage in IBD, cell viability was comparable between YOD1-deficient and -sufficient Mode-K cells, decreasing the possibility that YOD1 affects colitis by regulating the apoptosis of IECs." (PMID 39333628, 2024). "In aggregate, these results demonstrate that hematopoietic cell-derived YOD1 plays a key role in DSS-induced colitis." (PMID 39333628, 2024). "Consistently, PAS/AB staining showed that fewer goblet cells were maintained in Yod1−/− mice during DSS-induced colitis." (PMID 39333628, 2024). "In the present study, we found that NOD2-mediated protective responses in colitis were potentiated by YOD1, which inhibited the proteasomal degradation of RIPK2 by removing K48-linked polyubiquitin chains." (PMID 39333628, 2024). "Taken together, these results demonstrate that YOD1 is indispensable for NOD2-induced protective effects in experimental colitis." (PMID 39333628, 2024). "In contrast to MDP administration, LPS treatment ameliorated colitis in both Yod1+/+ and Yod1−/− mice (Fig. EV1A–I)." (PMID 39333628, 2024). "The bone marrow transplantation experiment reveals that YOD1 derived from hematopoietic cells inhibits DSS colitis." (PMID 39333628, 2024). "Taken together, these findings demonstrate that ablation of YOD1 aggravates experimental colitis in mice, indicative of a protective role of YOD1 in IBD." (PMID 39333628, 2024). "Here, we find that mice deficient of YOD1, a deubiquitinating enzyme, are highly susceptible to dextran sulfate sodium (DSS)-induced colitis." (PMID 39333628, 2024). "To directly confirm that YOD1 regulates colitis through RIPK2, we silenced RIPK2 in Yod1+/+ and Yod1−/− mice with adeno-associated virus (AAV)." (PMID 39333628, 2024). "Collectively, the findings of this study identified YOD1 as a novel regulator of NOD2 signaling and experimental colitis, and highlight the potential of YOD1 as a beneficial therapeutic target for IBD." (PMID 39333628, 2024). "To study the role of YOD1 in colitis, we generated Yod1−/− mice and found that ablation of YOD1 aggravated DSS-induced colitis." (PMID 39333628, 2024). "To investigate the functional role of YOD1 in colitis, we generated Yod1−/− mice." (PMID 39333628, 2024). "Interestingly, in sharp contrast to the finding that colitis induced the overall downregulation of YOD1 in colon tissue, YOD1 expression was upregulated in colon-infiltrating macrophages in both mice and humans during colitis." (PMID 39333628, 2024). "Similarly, mRNA and protein levels of YOD1 were also significantly reduced in the colon tissue of DSS-treated mice, indicative of a potential role of YOD1 in colitis." (PMID 39333628, 2024). "Due to the overwhelming amounts of IECs, the overall expression of YOD1 was markedly reduced in the colon during colitis, indicating that the reduced colonic expression of YOD1 is the consequence, rather than the cause, of colitis." (PMID 39333628, 2024). "During colitis, the expression of YOD1 was impaired in damaged IECs." (PMID 39333628, 2024). "In addition, our data extend the in vivo function of YOD1 and broaden the spectrum of regulatory proteins in colitis." (PMID 39333628, 2024).
colitis (continued). "This study identifies YOD1 as a protective protein in colitis, indicating that therapeutic approaches enhancing YOD1 abundance or activity may be beneficial for IBD treatment." (PMID 39333628, 2024). "Collectively, this study identifies YOD1 as a novel regulator of colitis." (PMID 39333628, 2024). "Therefore, this study demonstrates that YOD1 is an important protective regulator in colitis." (PMID 39333628, 2024). "In addition, we observed that YOD1 was upregulated in colon-infiltrating macrophages in both humans and mice during colitis, which may serve as a beneficial stress response to enhance the ability of macrophages to clear dissipated bacteria." (PMID 39333628, 2024). "Importantly, YOD1 is upregulated in colon-infiltrating macrophages in patients with colitis." (PMID 39333628, 2024). "Ablation of YOD1 attenuated the activation of NOD2-mediated signal transduction and functional outcomes in macrophages, leading to exacerbated colitis." (PMID 39333628, 2024). "To address the significance of YOD1 in NOD2 signal transduction in vivo, we studied the effect of MDP treatment on DSS colitis in Yod1+/+ and Yod1−/− mice." (PMID 39333628, 2024). "In summary, this study shows that YOD1 mediates optimal NOD2 signal transduction in macrophages and thereby ameliorates experimental colitis." (PMID 39333628, 2024). "The deubiquitinating enzyme YOD1 potentiates protective NOD2 signaling by stabilizing RIPK2, thereby ameliorating intestinal inflammation and colitis." (PMID 39333628, 2024). "However, colitis in Yod1−/− mice was still significantly more severe than that in Yod1+/+ mice after LPS administration (Fig. EV1A–I), showing that YOD1 is dispensable for TLR4 signaling in vivo." (PMID 39333628, 2024). "Moreover, Yod1+/+ and Yod1−/− mice had similar disease severity after RIPK2 knockdown, indicating that YOD1 affects colitis by regulating RIPK2." (PMID 39333628, 2024). "In line with published findings that NOD2−/− and RIPK2−/− mice are more susceptible to DSS-induced colitis than control mice, we found that Yod1−/− mice, accompanied with reduced RIPK2 levels, also developed more severe experimental colitis than did control mice." (PMID 39333628, 2024). "Noteworthily, YOD1 was mainly expressed in IECs under physiological conditions, but deletion of YOD1 had no impact on TNF-α-induced apoptosis of IECs, implying that YOD1 in IECs may be dispensable for colitis." (PMID 39333628, 2024). "Moreover, YOD1 deficiency did not change cytokine production and signal transduction in macrophages upon stimulation with TNF, a detrimental cytokine in colitis." (PMID 39333628, 2024).
colorectal cancer (1 paper, 2023). A primary or metastatic malignant neoplasm that affects the colon or rectum. "GEO survival analysis was conducted to screen TCF4 target genes associated with the survival of colorectal cancer patients, among which Cystic fibrosis transmembrane conductance regulator (CFTR), Tyrosine-protein kinase Fyn (FYN), and YOD1 deubiquitinase (YOD1) were considered to be eligible." (PMID 37337284, 2023).
lymph node metastasis (1 paper, 2023). "Subsequent analysis showed that YOD1 was markedly associated with T stage and lymph node metastasis." (PMID 37573347, 2023).
Machado-Joseph disease (1 paper, 2023). "GSEA also indicated that the transcriptional changes observed in Yod1 overexpressing flies are significantly enriched in datasets of models of two human diseases, HD (P = 0.017) and Machado-Joseph disease (Spinocerebellar Ataxia 3, P = 0.041), another polyQ induced neurodegenerative disorder." (PMID 38081944, 2023).
mucolipidosis II (1 paper, 2024). "N-acetylglucosamine-1-phosphotransferase subunit gamma (GNPTG) and N-acetylglucosamine-1-phosphotransferase subunit gamma (YOD1) are classically associated with mucolipidosis II/III and cancer, respectively." (PMID 38898508, 2024).
muscle atrophy (1 paper, 2026). The loss of muscle tissue due to inactivity or disease. "This study provides new insights into the post-translational regulation of muscle-specific E3 ligases and presents evidence showing that targeting YOD1 is a promising therapeutic approach for the prevention and treatment of muscle atrophy." (PMID 42052961, 2026).
nasopharyngeal carcinoma (1 paper, 2025). A carcinoma arising from the nasopharyngeal epithelium. "In contrast, other OTU members exert anti-cancer effects in specific cancers, such as YOD1 in HNSCC and cervical cancer; OTUD1 and OTUD6B in clear cell renal cell carcinoma (ccRCC); TNFAIP3 in nasopharyngeal carcinoma (NPC)." (PMID 40469292, 2025).
periodontitis (1 paper, 2025). An acute or chronic inflammatory process that affects the tissues that surround and support the teeth. "We not only identified a novel set of ISR-related biomarkers—BTG2, DERL3, FOS, HSPA13, and YOD1—but also revealed their potential associations with periodontitis-specific pathological features, such as osteoclast differentiation and the RANKL/OPG signaling pathway." (PMID 41459503, 2025). "In this study, BTG2, DERL3, FOS, and HSPA13 were significantly upregulated, and YOD1 was significantly downregulated in the gingival tissues of periodontitis patients, confirming their detectable presence locally." (PMID 41459503, 2025).
primary brain tumors (1 paper, 2023). "We identified a selected group of DUBs (USP13, USP14, USP19, USP25, OTUD2/YOD1) associated with the Regulation of ERAD pathway across several adult and pediatric primary brain tumors (GBM, EPN, CPh, MB)." (PMID 37892185, 2023).
protein misfolding disease (1 paper, 2023). "We were curious to find out whether the modulatory effects of Yod1 were specific for mutant Htt induced pathology or similar effects could be observed in other protein misfolding disease models." (PMID 38081944, 2023).
renal carcinoma (1 paper, 2025). A carcinoma arising from the epithelium of the renal parenchyma or the renal pelvis. "Additionally, YOD1 knockdown notably increased the proliferation of patient-derived renal cancer organoids, as well as ccRCC proliferation and metastasis, in vitro and in vivo." (PMID 40274778, 2025). "However, research on YOD1 in renal cancer is scarce, highlighting the need for investigations into its role and potential as a therapeutic target in this type of carcinoma." (PMID 40274778, 2025).
retinal (1 paper, 2023). "Neither flies expressing Httex1.Q25 alone, nor ones co-expressing Httex1.Q25 and Yod1 showed signs of retinal neurodegeneration or reduced viability." (PMID 38081944, 2023).
rheumatoid arthritis (1 paper, 2025). A chronic, systemic autoimmune disorder characterized by inflammation in the synovial membranes and articular surfaces. "Leonurus regulates the Hippo signaling pathway through the miR-21/YOD1/YAP axis to reduce joint inflammation and bone destruction in CIA mice, thereby inhibiting the growth and inflammation of rheumatoid arthritis fibroblast-like synoviocytes (RA-FLSs)." (PMID 40292098, 2025).
spina bifida (1 paper, 2020). A congenital neural tube defect in which vertebrae are not fully formed. "As a gene encoding deubiquitinating enzyme, YOD1 was predicted to be co-regulated by miR-142-3p and miR-144 in spina bifida." (PMID 33343629, 2020). "We therefore have reason to speculate that YOD1 plays a similar role in spina bifida." (PMID 33343629, 2020). "In this study, we identified a miRNA–mRNA regulatory network including four miRNAs and 39 mRNAs in spina bifida and implicate TSPAN6, YOD1, and KCND3, ubiquitylation pathways, and an antiviral immune response as modulators of neural tube malformations." (PMID 33343629, 2020).
squamous cell carcinoma (1 paper, 2025). A carcinoma arising from squamous epithelial cells. "Conversely, increased YOD1 expression blocks ERK signaling by stabilizing TRIM33 activation, thereby inhibiting tumor invasion and lymph node metastasis in squamous cell carcinoma of the head and neck." (PMID 40274778, 2025).
cancer (10 papers, 2021 to 2025). A tumor composed of atypical neoplastic, often pleomorphic cells that invade other tissues. "From the results of IHC, the expression level of YOD1 in cancer tissues was clearly lower than that in healthy tissues." (PMID 37573347, 2023). "The GEO data analysis showed that in patients suffering with HNSCC, YOD1 expression was lower in cancer tissues compared with adjacent tissues." (PMID 37573347, 2023). "On the whole, compared with the adjacent tissues, the expression of YOD1 in cancer tissues was high." (PMID 35642058, 2022). "In fact, it is reported that YOD1 is an important proliferation and metastasis-inducing gene, which can stimulate the characteristics of cancer stem cells and maintain circulating tumor cells (CTC)." (PMID 35642058, 2022). "In fact, some genes, such as HRAS, YOD1, VHL, and CEBPA, were among the most important genes for several cancer types even though their number of mutations in TCGA is very small compared to other genes (ranging from the 4th to 16th percentile)." (PMID 34385450, 2021). "The IHC results confirmed that YOD1 protein expression was much lower in cancer tissues than in normal tissues, suggesting that YOD1 may participate in HNSCC tumor progression." (PMID 37573347, 2023). "Our study provides novel insights into the regulatory mechanisms of YOD1 and USP21 in the context of the Hippo signaling pathway, and sheds lights on their potential as therapeutic targets for cancer treatment." (PMID 37743467, 2023).
tumor (10 papers, 2013 to 2025). "Knockdown of YOD1 markedly promoted subcutaneous tumor growth and lung metastasis, and these effects were reversed by ZNF24 overexpression." (PMID 40274778, 2025). "Overall, we conclude that YOD1 acts as a tumor suppression factor by attenuating tumor growth and metastasis through the ZNF24/VEGFA pathway in ccRCC." (PMID 40274778, 2025). "Cell proliferation was additionally evaluated by Ki67 positive expression and YOD1 expression of the mouse tumor tissues using triple immunofluorescence (IF)." (PMID 37667382, 2023). "In this study, for the first time, we identified the tumor-suppressive role of YOD1 in ccRCC." (PMID 40274778, 2025). "Notably, we constructed patient-derived ccRCC organoids and demonstrated that YOD1 silencing significantly accelerated organoid growth, further underscoring the critical tumor-suppressive function of YOD1 in ccRCC." (PMID 40274778, 2025). "Furthermore, overexpression of YOD1 reversed the tumor-suppressive effects observed after SOX21-AS1 knockdown." (PMID 40525874, 2025). "YOD1 exhibits tumor-suppressive effects by inhibiting the growth and metastasis of ccRCC." (PMID 40274778, 2025). "Thus, we propose that YOD1 is an important tumor suppressor worthy of further investigation in ccRCC." (PMID 40274778, 2025). "Notably, YOD1 knockdown significantly promoted the proliferation of tumor organoids derived from ccRCC patients." (PMID 40274778, 2025). "Yod1 Deubiquitinase (YOD1) is a protein coding gene that is expressed in tumor cells." (PMID 39115875, 2024). "YOD1 knockdown MDA-MB-231 cells were injected into nude mice through the tail vein and the bioluminescent imaging showed YOD1 knockdown could significantly decrease the tumor burden and metastasis." (PMID 37667382, 2023). "We also found that YOD1 may be closely related to the tumor immune microenvironment by IHC experiments." (PMID 35642058, 2022). "At the same time, expressing level of YOD1 is related to degree of tumor immune microenvironment." (PMID 35642058, 2022). "YOD1 is a highly conserved deubiquitinating enzyme belonging to the ovarian tumor (otubain) family, whereas its role and molecular mechanism remain unclear in mammalian cells." (PMID 34168678, 2021). "Interestingly, YOD1 may regulate distinct target genes in various tumors, thereby playing a role in either promoting or inhibiting tumor development." (PMID 40274778, 2025). "Moreover, YOD1 knockdown promoted tumor growth and metastasis in vitro and in vivo." (PMID 40274778, 2025). "Knowing that dysregulation of the cell cycle is an important reason for tumor proliferation, we then used flow cytometry to determine whether cell-cycle arrest was engaged in the downregulation of proliferation when YOD1 level was decreased or increased in BT-549 and MDA-MB-231." (PMID 37667382, 2023). "In addition, CDK1 inhibitors could eliminate the effect of YOD1 overexpression (the proliferation and resistance to cisplatin), which further elucidates the tumor promoting mechanism of the YOD1-CDK1 axis." (PMID 37667382, 2023). "It was speculated that when YOD1 was overexpressed, the tumor purity was higher." (PMID 35642058, 2022). "Finally, immunohistochemical staining found that downregulation of FIRRE could attenuate the protein level of YOD1 in xenograft tumor tissues." (PMID 34168678, 2021). "The expression of YOD1 and ZNF24 was significantly downregulated in tumor tissues, with a strong correlation between them." (PMID 40274778, 2025). "To further validate these findings, we performed immunohistochemical staining for YOD1 and ZNF24 in a tumor microarray for ccRCC (cohort 1), which consisted of 80 paired tumor and normal tissue samples and an additional 110 surgical tumor samples (cohort 2)." (PMID 40274778, 2025). "In PAAD, the expressions of OTUD1 (P = 1.06E−52), YOD1 (P = 2.20E−50) and OTUD5 (P = 1.53E−45) in tumor tissues were higher than those in normal tissues." (PMID 35642058, 2022).